MMP13 (matrix metallopeptidase 13)
Diseases named in the same sentence as MMP13 in open-access papers (continued):
Sharing a sentence is not in itself a finding about the gene and the disease.
keratoconus (7 papers, 2016 to 2025). A degenerative, structural disorder of the eye, characterized by a cone-shaped protrusion of the cornea. "The study revealed also a negative association between IL-6 and Th1, respectively, between MMP-13 and keratoconus index (KI)." (PMID 27563164, 2016). "Furthermore, an increased in tear matrix metalloproteinases (e.g., MMP-1 and MMP-13) and inflammatory mediators following eye rubbing has been observed in patients with keratoconus, which may be associated with the progression of keratoconus." (PMID 40606911, 2025). "CXL treatment significantly elevated MMP-13 in the tear fluid of keratoconus patients, which was partially attributed to the active form of the tissue plasminogen activator that activates the MMP pathway." (PMID 30402279, 2018). "MMP-13 was categorically reported in keratoconus, suggesting that it plays a role in intra- and extracellular pathological collagen destruction." (PMID 26881061, 2016). "A 60-second eye rubbing technique typically used by keratoconus patients had as a result a significant increase of MMP-13 in tears that has an important role in the apoptotic activity of the keratocytes." (PMID 27563164, 2016). "Elevated levels of interleukin- (IL-) 1b, IL-4, IL-5, IL-6, IL-8, and IL-17; tumor necrosis factor (TNF)-α, -β; interferon- (IFN-) γ; matrix metalloproteinase- (MMP-) 1, MMP-3, MMP-7, MMP-9, and MMP-13; Cathepsin B; and Lipocalin-1 have been found in the tears of patients with keratoconus." (PMID 26881061, 2016). "These factors may contribute to the pathogenesis of keratoconus; furthermore, studies have shown that post-rubbing tear samples from normal eyes exhibit high concentrations of IL-8, MMP-13, IL-6, TNF-α, and epithelial growth factor compared to contralateral control eyes." (PMID 40343259, 2025). "The study showed increased levels of gelatinases and collagenases (1.9 times higher), as well as elevated MMPs, cytokines (MMP-1, MMP-3, MMP-7, MMP-13, and IL-6), and TNF-alpha and TNF-beta in the keratoconus group compared with the normal group." (PMID 27563164, 2016). "Partly in line with these results, increased tear levels of MMP-1, MMP-3, MMP-7, MMP-9, and MMP-13; IL-4, IL-5, IL-6, and IL-8, and TNF-α, -β were found in keratoconus." (PMID 26881061, 2016). "In the current study, we have determined the associations between nine mediators (IL-6, IL-10, CXCL8/IL-8, CCL5/RANTES, MMP-9, MMP-13, TIMP-1, t-PA, and PAI-1) in the tear fluid of keratoconic patients covering the whole spectrum of the disease (from subclinical to manifest keratoconus)." (PMID 26881061, 2016).
lung adenocarcinoma (7 papers, 2015 to 2026). A carcinoma that arises from the lung and is characterized by the presence of malignant glandular epithelial cells. "MMP-13 was also remarkably expressed in minimally invasive and invasive lung adenocarcinoma in humans, independently of the mutation status." (PMID 26193700, 2015). "Amplification of another member of the metalloproteinase family, MMP13, promotes brain metastases specifically in Kras-mutant lung adenocarcinoma." (PMID 33014869, 2020). "Immunohistochemical staining of human lung adenocarcinomas for MMP-13 showed the significant increase of MMP-13 expression in invasive and minimally invasive adenocarcinomas, as compared to non invasive lesions." (PMID 26193700, 2015). "In conclusion, this study highlights the importance of MMP-13 in lung adenocarcinoma development, and emphasizes its relevance as a target for innovative molecular imaging." (PMID 26193700, 2015). "Data from the present study demonstrate that MMP-13 is expressed early during lung adenocarcinoma development." (PMID 26193700, 2015). "Some of these genes (HMGA2, MMP13, BIRC7, and PLA2G2D) have been reported to be overexpressed in various cancers, including lung adenocarcinoma, and are associated with tumor progression and metastasis, supporting their potential as biomarkers for PD-1 immunotherapy." (PMID 41529246, 2026). "Use of an MMP-specific fluorescent probe and a dual MRI-FMT imaging system in the K-rasLSL-G12D mouse model to detect and quantify tumor-associated activity in living mice led to the identification of MMP-13 expression as a potential marker of progression to lung adenocarcinoma." (PMID 26193700, 2015). "The amplifications of MYC, YAP1, and MMP13, as well as the deletion of CDKN2A/B, contributed to LC-BrMs originating from lung adenocarcinoma." (PMID 39593114, 2024). "Pathway enrichment analysis showed that MMP13 upregulation was correlated with activation of the EMT signaling pathway, which was verified by WB in lung adenocarcinoma tissues." (PMID 37000142, 2023).
metastatic tumors (7 papers, 2014 to 2023). "Liver metastases were stained for Ki67 (proliferation marker) and cleaved caspase-3 (apoptosis marker) to examine the role of MMP13 in promoting the survival and outgrowth of metastatic tumors." (PMID 25880591, 2015). "In conclusion, we have shown that MMP13 is elevated in the setting of hepatic steatosis and that both tumor and stromal derived MMP13 are involved in attenuating metastatic tumor burden in the liver." (PMID 25880591, 2015). "In addition, we detected increased expression of MMP-13 in the metastatic tumors overexpressing leptin, suggesting an important role of MMP-13 in leptin-induced cancer progression." (PMID 25948792, 2015). "Additionally, liver metastases were stained for Ki67 (proliferation marker) and cleaved caspase-3 (apoptosis marker) to further examine the role of MMP13 in promoting the proliferation and outgrowth of metastatic tumors." (PMID 25880591, 2015). "Given that MMPs are key proteins involved in the metastatic process, in the present study we evaluated the role of Pit-1 on the expression and biological activity of two collagenases, MMP-1 and MMP-13, whose role in several processes of the metastatic disease is well known." (PMID 25527274, 2014). "The highest differentially expressed genes in metastatic (MET and PRI+) versus non-metastatic tumors (PRI-) and SES included PLAU, PLAUR, MMP1, MMP10, MMP13, ITGA5, VEGFA, and various inflammatory cytokine genes." (PMID 35480116, 2022). "The first is the capacity of Everolimus to restrain the progression of skeletal metastatic disease in BC patients through a specific mechanism that includes inhibiting the release by these cells of the most effective pro-OC factors such as M-CSF, TNFα, IL-1β, IL-6, MIP-1α and MMP-13." (PMID 26468083, 2015). "MMP7, MMP13, and MMP10 were upregulated, and MMP12 and MMP9 were downregulated in metastatic tumours compared with nonmetastatic tumours." (PMID 31996191, 2020). "MMP7, MMP13, and MMP10 were upregulated in metastatic tumours compared with nonmetastatic tumours." (PMID 31996191, 2020).
oral cancer (7 papers, 2016 to 2023). "Previous reports showed that MMP13 could regulate tumor aggressiveness in oral cancer via the HBP1-MMP13 axis and can act as a diagnostic and prognostic molecular marker in HNSCC." (PMID 35690612, 2022). "Treatment with >5 μM EGCG suppressed the expression and activity of MMP13 in oral cancer OEC-M1 cells, suggesting an anticancer effect of EGCG through the downregulation of MMP13." (PMID 36677584, 2023). "F. nucleatum can induce the production of various matrix metalloproteinases (MMPs), such as MMP-9 and MMP-13, which have been used in monitoring and detecting metastatic phenotypes in oral cancer." (PMID 31993418, 2019). "Authors and Oncotarget editors agree to retract the article “MMP-13 is Involved in Oral Cancer Cell Metastasis” after concerns regarding data duplication in multiple figures were confirmed through an internal investigation." (PMID 27885991, 2016). "It has been reported that MMP-13 could promote the invasion, migration, and adhesion abilities of oral cancer cells." (PMID 31996191, 2020). "The expression levels of MMP7, MMP13 and MMP10 were validated to be significantly upregulated in oral cancer compared with normal samples according to the data mining of published profiles in Oncomine." (PMID 31996191, 2020).
adenoma (6 papers, 2003 to 2023). A neoplasm arising from the epithelium. "The characterization of the CRC-specific biomarker MMP-13 should facilitate objective and early detection of high grade adenomas and carcinomas." (PMID 27716617, 2016). "Especially the strong increase in MMP-13 IRS from low to high grade adenoma defines an early timepoint of beneficial MMP-13 staining as early predictive cancer marker." (PMID 27716617, 2016). "The percentage of TIMP-2- and MMP-13-positive fibroblasts was higher in adenomas than in carcinomas." (PMID 21726449, 2011). "Immunohistochemical staining revealed that TIMP-2 and MMP-13 were more highly expressed in simple adenomas than in simple carcinomas." (PMID 21726449, 2011). "Moreover, the upregulation of MMP-13 IRS from low to high-grade adenoma was considered an early predictive cancer biomarker." (PMID 34944846, 2021). "Moreover, in high grade adenoma and cancer samples bands of activated MMP-13 point out functionalization of MMP-13 during cancerogenesis." (PMID 27716617, 2016). "In low grade adenomas we detected a weak MMP-13 staining in 45% of the samples." (PMID 27716617, 2016). "MMP-13 IRS > 2.5 (ROC 97.67% sensitivity) comprises high grade adenoma and carcinoma." (PMID 27716617, 2016). "In healthy tissue and low grade adenomas only weak signals could be detected, whereas in high grade adenoma and carcinoma stronger signals and bands of activated MMP-13 appeared." (PMID 27716617, 2016). "RT-qPCR identified Mmp-13 as the main Mmp expressed in both in adenomas and carcinomas." (PMID 26193700, 2015). "In addition to MMP-7 expression, 60–65% of Min adenomas express MMP-2 and MMP-10 (stromelysin-2) and 50% express MMP-3 and MMP-13 (collagenase) with expression limited to the stroma surrounding the adenoma." (PMID 12778076, 2003). "According to the strength of the association between pathologic stage and immunoreactivity scoring (IRS) of MMP-13, in high-grade adenomas and CRC, MMP-13 was observed with a moderate and strong staining intensity, respectively." (PMID 34944846, 2021). "We demonstrate that MMP-13 expression, quantitatively assessed by a newly adopted IRS and verified by Western blotting, increased with pathological stage of adenoma and carcinoma development." (PMID 27716617, 2016). "The immunoreactivity for MMP-13 and TIMP-2 was lower in carcinomas than in adenomas, confirming the mRNA data for MMP-13 and the other MMP inhibitors that were evaluated." (PMID 21726449, 2011).
intervertebral disc degeneration (6 papers, 2019 to 2024). "Previous findings have shown that estrogen can protect cartilage and inhibit intervertebral disc degeneration by suppressing catabolic activity of protease (MMP-13)." (PMID 38877549, 2024). "A specific catabolic gene (MMP13) is essential for intervertebral disc degeneration pathogenesis." (PMID 34488795, 2021).
invasive breast carcinoma (6 papers, 2008 to 2023). A carcinoma that infiltrates the breast parenchyma. "A study of 263 cases of invasive breast cancer revealed MMP13 expression by both tumor cells and adjacent fibroblasts, with high levels of MMP13 in these two cell types strongly correlated with each other." (PMID 22253746, 2012). "In line with its potential role in DCIS, data from publicly available invasive breast carcinoma repositories showed that while high RNA expression of β6 in the bulk tumour was associated with higher levels of EP300, MMP13 expression was also significantly increased in high EP300 expressing patients." (PMID 36864079, 2023). "Matrix metalloproteinase-13 (MMP-13) is a hypothetical prognostic marker in invasive breast cancer." (PMID 34452576, 2021). "MiR-941 inhibitor increased the expression of E-cadherin (Epithelial cell marker) and decreased the expression of MMP-13 (tumour marker for invasive breast cancer) respectively in MDA-MB-231 cells, which further confirms the role of miR-941 in migration and invasion of MDA-MB-231 cells." (PMID 33087811, 2020). "Our previous studies of human DCIS with early invasion led us to hypothesize that MMP13 would be a fibroblast-derived, potential rate-limiting proteinase in the transition from non-invasive to invasive breast carcinoma." (PMID 18698413, 2008). "MMP-13 may serve as an independent prognostic factor for invasive breast cancer patients." (PMID 18373849, 2008).
invasive ductal carcinoma (6 papers, 2008 to 2021). "Mmp13 mRNA is expressed by a subpopulation of myofibroblasts in human invasive ductal breast carcinomas, but is rarely expressed in normal breast, benign breast lesions and ductal carcinoma in situ (DCIS)." (PMID 18698413, 2008). "Mmp13 mRNA is expressed in a subpopulation of myofibroblasts in invasive ductal breast carcinomas, but rarely in normal breast, benign breast lesions and ductal carcinoma in situ (DCIS)." (PMID 18698413, 2008). "Finally, we evaluated Pit-1, MMP-1, and MMP-13 protein expression in 110 human breast invasive ductal carcinomas." (PMID 25527274, 2014). "This study aimed to determine MMP-13 expression in benign and malignant breast lesions and to evaluate the correlation between MMP-13 expression and tumor characteristics in invasive ductal carcinoma (IDC)." (PMID 34452576, 2021).
non-small cell lung carcinoma (6 papers, 2018 to 2024). A group of at least three distinct histological types of lung cancer, including non-small cell squamous cell carcinoma, adenocarcinoma, and large cell carcinoma. "Higher MMP-13 expression is also associated with lymph node metastasis and poor prognosis in bladder and non-small cell lung cancers and with poorer patient survival in breast, prostate and head and neck cancers." (PMID 35805035, 2022). "Combined detection of SNP and enzyme activity between MMP9 and MMP13 is expected to be a potential diagnostic method for non-small cell lung cancer." (PMID 30889876, 2019). "Combined detection of SNP and enzyme activity between MMP9 and MMP13 are expected to be a potential diagnostic method of non-small cell lung cancer." (PMID 30889876, 2019). "The objective of this study aim to evaluate the serum levels and polymorphisms of MMP-9 and MMP-13 in non-small cell lung cancer patients compared to normal subjects and their correlation to non-small cell lung cancer histopathology findings in Southern Chinese people." (PMID 30889876, 2019). "Over 50% higher MMP-13 expression is seen in bladder and non-small cell lung cancers, particularly at the invading front of the tumours." (PMID 35805035, 2022). "Recently, Hu and Lu demonstrated that c-MYC activates the long noncoding RNA brain cytoplasmic RNA 1 (BCYRN1), which in turn promotes metastasis in non-small-cell lung cancer (NSCLC) by secreting MMP9 and MMP13." (PMID 39338293, 2024). "In non-small cell lung cancer, Hu and Lu found c-MYC activated BCYRN1 to promote tumor cell metastasis through up-regulating MMP-9 and MMP-13." (PMID 31652309, 2019). "In non-small-cell lung cancer cells, the number of migrated and invaded cells and the expression of metastasis-supporting proteins MMP9 and MMP13 changed with the regulation of BCYRN1." (PMID 29435146, 2018).
Peri-Implantitis (6 papers, 2013 to 2025). An inflammatory process with loss of supporting bone in the tissues surrounding functioning DENTAL IMPLANTS. "The qualitative evidence indicates that certain polymorphisms—particularly in the CD14, TNFα, IL-1, and EGF genes—show consistent associations with increased susceptibility to peri-implantitis, while others (e.g., MMP13, TGFB3, RANKL) demonstrate no clear relationships." (PMID 41373620, 2025). "Collagenase-3 or MMP-13 is another collagenolytic MMP with exceptionally wide substrate specificity and also a role in peri-implantitis." (PMID 24490073, 2013).
renal fibrosis (6 papers, 2013 to 2024). A final common manifestation of a wide variety of chronic kidney diseases characterized by glomerulosclerosis and tubulointerstitial fibrosis. "The data showed a significantly increased expression of MMP-9 and the decreased expressions of MMP-7 and MMP-13 were associated with UUO-induced renal fibrosis." (PMID 35754468, 2022). "Elevated expression of MMP-9 and MMP-13 was reported to be associated with renal fibrosis in DN25,42,43." (PMID 36522378, 2022). "Another study defining the role of cytokine cardiotrophin 1, in cardiac, vascular, and renal function found increased renal fibrosis with cardiotrophin 1 infusion which was associated with a decreased MMP-13/TIMP-1 ratio suggesting a protective role in this model." (PMID 24159376, 2013). "Our study showed that miR-1470 could bind to the 3'-UTR of MMP13, inhibiting its expression and reducing the degradation of the extracellular matrix, which promoted the process of renal fibrosis." (PMID 38316653, 2024). "Inhibiting the high expression of MMP13 in the pathological state may be a target for improving renal fibrosis, and EA can inhibit MMP13." (PMID 37831322, 2023). "In addition, upregulated MMP-9 and MMP-13, excessive collagen deposition in the glomerular and tubulointerstitial regions, and degradation of vascular elastin resulted to renal fibrosis in the Akita mice." (PMID 36522378, 2022). "In conclusion, it indicates that miR-1470 can bind directly to MMP13, while miR-4483 binds to TIMP1 and thus is involved in renal fibrosis." (PMID 38316653, 2024). "Therefore, we believe that EA can attenuate renal fibrosis by regulating the extracellular matrix of renal tubular epithelial cells, and its mechanism may be partially mediated by inhibiting the high expression of MMP13." (PMID 37831322, 2023). "In this study, we also identified that the regulation of fibrosis via targeting MMP13 and TIMP1 may be the mechanisms by which miR-1470 and miR-4483 are involved in the process of renal fibrosis." (PMID 38316653, 2024).
thyroid cancer (6 papers, 2010 to 2021). "Many MMP family members, such as MMP2, MMP7, MMP9, MMP11, and MMP13, have been implicated to be associated with the development and progression of thyroid cancer." (PMID 28709407, 2017). "These MMPs are significant in that they are regulated by NF-κB (MMP-9) and expressed ubiquitously in thyroid cancer cell lines (MMP-13)." (PMID 20492683, 2010). "Proteomic studies on PTC tissue from humans have suggested NTRK1, metalloproteinases (MMP-1, MMP-9 and MMP-13) and Cathepsins (-W and -X), NF-KB and other apoptosis associated proteins as radiation-induced PTC biomarkers, together with SPANXA as an important protein for thyroid cancer development." (PMID 33382739, 2020). "In thyroid cancer, hsa_circ_0074817 targets miR-27a-3p, targeting MET, ABCA1, MMP13, and PLAG1, promoting cell proliferation, invasion, and metastasis in thyroid carcinoma." (PMID 34055888, 2021). "To investigate the mechanism by which NF-κB regulates thyroid cancer cell invasion, we performed quantitative RT-PCR to examine the NF-κB-dependent regulation of the matrix metalloproteinase (MMP) -2, MMP-9, and MMP-13." (PMID 20492683, 2010).
asthma (5 papers, 2019 to 2025). "Levels of BMP4 have correlated with FEV1 and FEV1/FVC in asthma, while in vitro studies demonstrate that MMP13 limits bronchial epithelial repair as it is a protease that degrades fibrinogen and matrix proteins essential for epithelial repair." (PMID 40131902, 2025). "We screened seven candidate diagnostic biomarkers for asthma using LASSO regression (namely, BCL10, CD300E, IER2, MMP13, OAF, TBC1D3, and TMEM151A), among which the area under the curve (AUC) value for CD300E and IER2 were 0.722 and 0.856, respectively." (PMID 37259023, 2023). "Other authors also showed increased activities of elastinolytic MMP-9 and MMP-13 as well as collagenolytic MMP-8 in equine asthma." (PMID 31316303, 2019). "Elevated levels of MMP-9 and MMP-13 were found in the serum, sputum and BALF of patients with classic asthma." (PMID 35721212, 2022).